TIAM1 (TIAM Rac1 associated GEF 1)
Diseases named in the same sentence as TIAM1 in open-access papers (continued):
Sharing a sentence is not in itself a finding about the gene and the disease.
cancer (continued). "Therefore, blocking the Tiam1/Rac1 interaction has the potential to reduce metastasis from multiple cancer types." (PMID 32322580, 2020). "Other hypermethylated age DMR genes from our data set classified two pathways relevant for growth and development (DCP1B, IGF1R, and FGF18) and cancer progression (TIAM1)—biological processes which has been also mentioned in the literature as epigenetic hallmarks of aging." (PMID 31281827, 2019). "Moreover, inhibition of TIAM1 expression in CAFs inhibit drug resistance and highlights the importance of suppressing TIAM1 expression in both cancer cells and CAFs." (PMID 30890693, 2019). "At the same time, we identified that TIAM1 expression in cancer cells was significantly higher, which could in turn upregulate the expression of TIAM1 in the CAFs." (PMID 30890693, 2019). "In the present study we investigated whether TIAM1 can be used as a potential therapeutic target not only for cancer cells, but surrounding stromal cells." (PMID 30890693, 2019). "Based on the outcome of cancer genome resequencing, TIAM1 downregulation is not typically achieved through mutation." (PMID 28416184, 2017). "Our findings confirm that high Tiam1 expression in the carcinomas of the oral cavity, glottis, and supraglottic larynx predicts poor clinical outcomes, suggesting that Tiam1 might be a new molecular biomarker of this disease." (PMID 26369827, 2015). "Further studies are required to establish the regulatory network of Tiam1 in cancer progression." (PMID 24069171, 2013). "Tiam1 is suggested to play a role in the development and progression of human cancers." (PMID 24069171, 2013). "Moreover, in vivo studies showed that Tiam1 involved in cancer development and metastasis in nude mice." (PMID 24069171, 2013). "Indeed, p140Cap is able to reduce cancer cells aggressiveness through specific molecular mechanisms, such as the down-regulation of Src kinase activity, and the Rac-Tiam1 axis, or by inhibiting the β-Catenin activity in cancer stem cells and modulating the immune tumor microenvironment." (PMID 38123597, 2023). "Therefore, the role of Tiam1 in cancer progression remains controversial." (PMID 36446524, 2023). "However, TIAM1 also exhibits context-dependent roles in cancer." (PMID 37748077, 2023). "However, investigations have suggested that Tiam1 has opposite effects on different cancers." (PMID 24069171, 2013). "Further validation in four independent cohorts showed that KEAP1, SRI, MFAP1, MFAP2, INCENP, and KIF21B were consistently upregulated in cancer tissues, while MYOZ3, DST, and TIAM1 were consistently downregulated." (PMID 40228435, 2025). "Supporting this, our RNAseq data show decreased expression of pro-migratory and pro-invasive genes, such as Fermt2 and Tiam1, in ephrinB2 knockout MOC2 cancer cells." (PMID 39489818, 2025). "Interrogation of the Broad Institute Cancer Cell Line Encyclopedia indicates that TIAM1 and Nur77 mRNA are also enriched in SCLC compared to other cancer cell lines, suggesting a selective role for this cell survival regulatory pathway in SCLC." (PMID 34758330, 2021). "For example, CtBP2 can activate Tiam1 (T cell lymphoma Invasion and Metastasis 1) in an NADH-dependent manner, thereby promoting cancer cell migration." (PMID 32549759, 2020). "The activity of T-cell lymphoma invasion and metastasis 1 (TIAM1), a Rac guanine nucleotide exchange factor (GEF), crucial for cell adhesion and migration, has been demonstrated to be upregulated in some cancers." (PMID 33126517, 2020). "TIAM2 and its homologue TIAM1 act as RAC GTPases in cell motility, and are involved in cancer cell invasion and metastasis." (PMID 30817801, 2019). "miR-21 promotes migration of cancer cells by targeting Reversion Inducing Cysteine-Rich Protein with Kazal motifs (RECK), TIMP metallopeptidase inhibitor 3 (TIMP3), and T-Cell Lymphoma Invasion And Metastasis 1 (TIAM1) genes." (PMID 29491883, 2018).
cancer (continued). "In part, this may be due to Tiam1’s ability to regulate E-cadherin expression, since loss of E-cadherin expression is considered to be a signature event in Epithelial-Mesenchymal transition (EMT), which is the reverse process of MET and has a pivotal role in cancer invasion and metastasis." (PMID 27562113, 2016). "Having demonstrated that TIAM1 and TRIM28 promote EMT via downregulation of E-cadherin, and that they directly repress protocadherins, which themselves can regulate EMT in cancer, we analyzed the functional significance of this regulation on NSCLC cell migration." (PMID 37748077, 2023). "To investigate the interaction between TIAM1 and stemness, we performed a sphere formation assay with cancer cells with or without TIAM1 inhibition." (PMID 30890693, 2019). "Certainly, MTSS1 and TIAM1 were almost absent in G10 cells, as described in metastatic and poor prognosis cancers." (PMID 27206673, 2016). "Considering that TIAM1 suppression resulted in an improved sensitivity towards the three CRC therapeutic drugs, we hypothesized that TIAM1 may mediate chemoresistance through regulation of cancer stemness." (PMID 30890693, 2019). "Therefore, we hypothesized that CAFs contribute to overexpression of TIAM1 in CRC, which subsequently manifests in increased chemotherapeutic resistance in cancer patients." (PMID 30890693, 2019). "Taken together these data demonstrate the ability of Tiam1 and P-Rex1, irrespective of upstream signalling, to induce cell morphological changes and actin cytoskeletal rearrangements that govern Rac1-driven anti- and pro-migratory phenotypes, respectively, in both normal and cancer cell lines." (PMID 26887924, 2016).
infection (8 papers, 2010 to 2023). The state of being infected such as from the introduction of a foreign agent such as serum, vaccine, antigenic substance or organism. "After ST infection, TIAM1 expression in the selected line was significantly up-regulated in the spleen and cecal tonsils, which are rich in heterophils and macrophages." (PMID 36807561, 2023). "In contrast to the perfused tissue, the lavage samples showed normal bacterial titre, neutrophil recruitment, and overall leukocyte number, suggesting that Tiam1 is dispensable for clearing the infection from the airways." (PMID 38077328, 2023). "Initially we elucidated whether the specific inhibitor NSC23766, which prevents the interaction of Rac1 with its GEFs Tiam1 and Trio, exerts an antiviral effect against IV infection in cultured cells." (PMID 24523909, 2014). "Infection of TZM-BL cells with A-MLV-ENV-HIV-1 or VSV-G-HIV-1 was not affected by expression of the targeted siRNAs, suggesting that Tiam-1, Abl, IRSp53, Wave2, and Arp3 are required for HIV-1 Env-mediated entry and are not necessary for post-fusion steps in the virus life cycle." (PMID 20585556, 2010).
neurodevelopmental disorder (3 papers, 2023 to 2024). A behavioral and cognitive disorder with onset during the developmental period that involves impaired or aberrant development of intellectual, motor, or social functions. "Potentially damaging CNVs (pdCNVs) provided support to the involvement of inherited variants in PHF3, NEGR1, TIAM1 and HOMER1 in neurodevelopmental disorders (NDD), although mostly acting as susceptibility factors with incomplete penetrance." (PMID 37961520, 2023).
neurological disease (2 papers, 2010 to 2020). "While phosphorylation of TIAM1 has been studied in relation to neurological disease, the posttranslational deimination of TIAM1 identified here in alligator has not been identified in any species so far to our knowledge." (PMID 32411128, 2020).
psychiatric disorder (2 papers, 2016 to 2025). A disorder characterized by behavioral and/or psychological abnormalities, often accompanied by physical symptoms. "For example, miR-190a-3p is significantly associated with POCD and regulates the gene Tiam1, which is involved in pathways related to psychiatric disorders and brain development." (PMID 40718798, 2025).
adenocarcinoma (1 paper, 2014). A common cancer characterized by the presence of malignant glandular cells. "Immunohistochemical staining for Tiam1 was performed on 98 adenocarcinoma and 30 normal lung tissues." (PMID 24661909, 2014).
bacterial infection (1 paper, 2023). "To assess whether Tiam1 is important for combatting acute bacterial infection, we infected wild type and Tiam1–/– mice intranasally with 2 x 106 CFU of S. pneumoniae and assessed bacterial titre and neutrophil recruitment into the lung 6 h later." (PMID 38077328, 2023).
infectious disease (1 paper, 2016). A disorder directly resulting from the presence and activity of a microbial, viral, or parasitic agent in humans. "Moreover, the question of whether Tiam1/Rac1 signalling in T cells influences the pathogenesis of other autoimmune or infectious diseases is intriguing." (PMID 27725632, 2016).
TIAM1 also shares sentences with these, for which no sentence is quoted: nasopharyngeal carcinoma (3 papers); papillary thyroid carcinoma (3); gallbladder carcinoma (2); head and neck squamous cell carcinoma (2); leukemia (2); Parkinson disease (2); acute pancreatitis (1); amyotrophic lateral sclerosis type 1 (1); anemia (1); atherosclerosis (1); autism (1); benign prostatic hyperplasia (1); Cerebral ischemia (1); cervical intraepithelial neoplasia (1); Chagas disease (1); cyst (1); digestive system tumors (1); endotoxemia (1); epilepsy (1); esophageal adenocarcinoma (1); esophageal cancer (1); fibrosarcoma (1); giant-cell lung carcinoma (1); gynecological cancers (1); Hypertension (1); in situ ductal carcinomas (1); keratoacanthoma (1); liver disease (1); malignant intestinal tumors (1); mantle cell lymphoma (1).
A further 13 diseases each share a sentence with TIAM1 in 1 paper.